ID4 (inhibitor of DNA binding 4)
Diseases named in the same sentence as ID4 in open-access papers (continued):
Sharing a sentence is not in itself a finding about the gene and the disease.
tumor (continued). "Among the 21 ODG tumors examined, expression of Id4 was seen in some reactive astrocytes but was essentially negative in neoplastic oligodendrocytes, while unequivocal Id4 staining was observed in some neurons associated with tumor cells (data not shown)." (PMID 16018821, 2005). "Collectively, these findings suggested that Id4 might be a novel tumor suppressor in the CRC." (PMID 33936204, 2021). "Moreover, markedly smaller tumors were found in nude mice after HCT116-Id4 cells inoculation as compared to the control group (P < 0.05), which illustrated that Id4 could significantly inhibit the growth of xenograft tumor in the nude mice." (PMID 33936204, 2021). "Although the methylation state of Id4 gene promoter in the CRC still needs to be investigated thoroughly, Id4 might be a tumor suppressor in the CRC according to our findings that the Id4 expression was very low in the CRC cells than in the normal mucosal cells." (PMID 33936204, 2021). "In this work, we hypothesize that ID4 may behave as a tumor suppressor in an ER+ cellular context." (PMID 30139383, 2018). "During tumorigenesis, ID4 may act as a tumor suppressor or as an oncogene in different tumor types." (PMID 30139383, 2018). "We speculate that at the molecular level, ID4 may integrate multiple regulatory pathways for example epigenetic re-programming, integration of multiple AR co-regulators or signaling pathways that may ultimately result in tumor suppressor activity of ID4." (PMID 27487149, 2016). "Mechanistically, ID4 may assimilate multiple regulatory pathways for example epigenetic re-programming, integration of multiple AR co-regulators or signaling pathways resulting in tumor suppressor activity of ID4." (PMID 27487149, 2016). "Thus, a decrease in ID4 expression levels could be one of the mechanisms adopted by cellular senescence to antagonize the tumor development in pre-cancerous cells." (PMID 24905922, 2014). "Thus, even in cancers arising from the same organ such as the breast, Id4 may act as both tumor suppressor and tumor promoter." (PMID 23342267, 2012). "Thus, one of the mechanism by which Id4 may exert its tumor suppressive effect is through up-regulation of E12/E47 bHLH proteins that may in turn up-regulate p21 expression at transcriptional level." (PMID 19500415, 2009). "Quantitative evaluation revealed consistent downregulation of ADH1B, CCL27, ID4 and LRP4 in tumor tissues compared to normal counterparts." (PMID 40296873, 2025). "They showed that mice that overexpressed ID4 and SOX2 had significantly higher tumor weight after carmustine treatment when compared to wild-type mice." (PMID 39861164, 2025). "In summary, our findings reveal that four of the identified characteristic genes (ADH1B, CCL27, ID4 and LRP4) are consistently downregulated in cSCC, and prior studies suggest their involvement in tumor proliferation, migration and invasion." (PMID 40296873, 2025). "DSEL, ID4, REEP2, and TMSB15A were upregulated in the NPC samples compared with the non-tumor samples." (PMID 38532632, 2024). "ID4 is an miR-342-3p target, and inhibitor Of DNA binding 4 (ID4) inhibition in BC cells increased MCF-7 chemo-sensitivity and suppressed tumour growth and EMT in vivo." (PMID 37670020, 2023). "Silencing of HOXA9 in ID4 overexpressing IOSE-M cells resulted in inhibition of anchorage-independent growth, and tumor formation, but had a moderate effect on cell proliferation." (PMID 33488950, 2020). "EZR-negative tumor cells also show the significant upregulation of CD109, ID4, ST8SIA1, and NR4A1 genes." (PMID 32679794, 2020). "Consistent with the role of SAM as a methyl donor, NCT-503 decreased DNA and histone methylation, and led to the re-expression of ID4, KLF4, CDKN2B and TXNIP tumor suppressors." (PMID 32138178, 2020).
tumor (continued). "Correlations between ID4 expression and the expression of FOXA1, ESR1, GATA3, CCND1, AKT, and IGF1R in the complete tumor cohort (ER+ and ER−)." (PMID 30139383, 2018). "To examine the relationship between these two transcripts in individual tumor specimens, we plotted the transcript abundances of BRCA1 versus ID4." (PMID 27077368, 2016). "The tumor suppressor activity of ID4NC was investigated in vitro and in vivo in castration resistant PCa cell line LNCaP in which ID4 was knocked down via gene specific shRNA." (PMID 27487149, 2016). "HLTF, BNIP3, H2AFX, CACNA1G, TGIF, ID4 and CACNA1A were identified as novel tumor suppressor candidates methylated in lung tumors." (PMID 20849603, 2010). "Furthermore, the present study found a strong correlation between the expression of target genes (IL10RB, INHBB, NEO1, PIK3R1, BCL2, ID4, and INHBA) and the infiltration of tumor-killing cells into the tumor immune microenvironment in HNC." (PMID 40647469, 2025). "In patient 2 (primary FL to relapse FL after a 2-year gap), there was a significant increase in Tumor B1 cells (from 2.89% to 74.56%), indicating that TFs enriched in Tumor B1, such as ZEB1, SNAI2, and ID4, may drive FL relapse." (PMID 41238550, 2025). "While there is substantial evidence supporting the involvement of S100A9 in the tumor immune microenvironment and immune evasion, the roles of CCL27, ID4 and LRP4, genes that also showed strong correlations with infiltrating immune cells, remain inadequately explored." (PMID 40296873, 2025). "Compared to non-tumor samples, REEP2, TMSB15A, DSEL, and ID4 were upregulated in NPC samples." (PMID 38532632, 2024). "Since genes highly expressed in the immune microenvironment are expected to have negative associations with tumor purity, ID4, and STON1 which had an unsignificant association with tumor purity (p > 0.05) were excluded." (PMID 35432538, 2022). "The top downregulated genes [WIF1, DACT2, ID4, TP63, SOX10] in tumours in our transcriptomic profile were regulators of Wnt signalling, cell differentiation and morphogenesis and acted as inhibitors of tumour growth in BC31–34." (PMID 34997107, 2022). "Importantly, by performing cosmic analysis in 35 tumor lines, we found that the ID4 as well as stem cell/EMT pathway targets significantly predict sensitivity of tumor cells to MK2206 (ID4 pathway, p = 0.037; stem cell/EMT pathway, p = 0.030)." (PMID 36291790, 2022). "Similarly, DNMT1 upregulation and TET downregulation accompanied ID4 methylation in cSCC tissues, collectively suggesting that ID4 is downregulated by UVR irradiation via DNA methylation and acts as tumor suppressor gene in cSCC development." (PMID 34298617, 2021). "Comparably, other authors have studied ID4 expression at the protein level in BC specimens and found correlations with high tumor grade, absence of HR, increased vascularization and recurrence, and shorter OS." (PMID 33514024, 2021). "In these tissue samples (n = 13), only four genes ID4, HMGCR, ROCK1, and CPT1A were differentially expressed (unadjusted p < 0.01), and no gene expression signatures were significantly different between primary tumor and baseline metastasis samples." (PMID 33428680, 2021). "Among the tumor cell lines, MCF-7 presented the highest levels of ID4 expression." (PMID 33514024, 2021). "Id4, a member of the Id (inhibitor of DNA binding) family of proteins, has been demonstrated to downregulate the expression of BRCA1 in in vitro and in-patient tumor samples." (PMID 32235500, 2020). "Importantly, in parallel to changes in DNA and histone H3 methylation status, we found a marked re-expression of methylation-regulated tumor suppressor genes: CDK2NB, KLF4, ID4, and TXNIP." (PMID 32138178, 2020). "Induced expression of ID4 in immortalized ovarian surface epithelial cells (IOSE-M, expressing SV40 large T & small t antigens, hTERT, and MEKDD) resulted in increased colony formation and tumor growth in mice." (PMID 33488950, 2020).
tumor (continued). "Therefore, we examined the expression level of four ID proteins and found that ID4 protein expression was significantly elevated in T-GFP-P cells and in tumor tissues derived from co-injection models." (PMID 30804471, 2019). "Additionally we selected seven other genes, ATF3, ADAMTS1, EGFR, PRNP, IGFBP6, ID4 and FN1, found to be differentially expressed according to tumor subtype and ER+/ER- classification from the tumor-specific differentially expressed gene-set." (PMID 19116033, 2008). "Normal breast tissues (n = 13) were analysed by MSP as well and did not exhibit any ID4 promoter methylation (data not shown), indicating that this is a tumour-specific process." (PMID 18513385, 2008). "Not only have known tumor suppressor genes like Cdkn2a (p16), Itga4 (α 4-integrin), and Igfbp7 been identified as targets of aberrant methylation in cancer by RLGS, but also novel tumor suppressor genes such as TCF21, SLC5A8, ID4, BMP3B, and SOCS1 have been identified by RLGS." (PMID 18053125, 2007). "A second basal/myoepithelial cluster highly expressed in Group III and IV tumors and a subset of DMBA tumors with squamous morphology was characterized by high expression of ID4, TRIM29, and Keratin 5, the latter of which is another human basal-like tumor marker." (PMID 17493263, 2007). "Id4 immunoreactivity was found in 10% to 100% of tumor cells in 12 of the 13 GBM specimens we examined (92%), and Id4 in both nucleus and cytoplasm could be detected in immunoreactive cells." (PMID 16018821, 2005). "Unlike protein expression, we found that Id4 mRNA had similar levels in specimens derived from all three tumor types examined in this analysis (p = 0.6)." (PMID 16018821, 2005). "Additionally, the Pearson correlation analysis results showed that protein levels of Id4 did not correlate with mRNA levels in tumor (r = −0.108, P = 0.592) or non-tumor (r = −0.010, P = 0.960) tissues." (PMID 28143562, 2017). "In contrast, Id4 has been detected neither in normal cerebellum nor in tumor cells." (PMID 28122577, 2017). "We speculate that Id4 may have unique bHLH or non-bHLH interaction partners that could largely define its tumor-promoting versus tumor-suppressive functions." (PMID 23342267, 2012). "Whether ID4 positively influences tumor growth is still not completely understood." (PMID 20070914, 2010). "Their findings show, that ID4 regulates the AR activity by interaction with FKBP52, whereas in absence of ID4 FKBP52 potentiates AR signaling and leads to increased proliferation and tumor growth." (PMID 30568592, 2018). "Our data also suggest that in the absence of ID4, FKBP52 significantly potentiated AR signaling leading to increased proliferation and tumor growth." (PMID 28252832, 2017). "For example, AR in L(-)ID4 cells and prostate epithelial cells from Id4−/− mice fails to express NKX3.1 (a homeodomain protein), an androgen activated PCa tumor suppressor." (PMID 27487149, 2016). "Two of the 10 patients with OAC have died; one tumor had no detectable Id4 and FABP7 immunoreactivity, while the other one showed a similar degree of cytoplasmic/nuclear FABP7 and cytoplasmic Id4 staining to the other 4 specimens derived from patients who were still alive." (PMID 16018821, 2005). "However, the expression of DSEL, ID4, REEP2, and TMSB15A not related the tumor progression." (PMID 38532632, 2024). "Notably, ID4 has not been found in CRC samples and seems to be rare in tumours in general." (PMID 34843512, 2021). "The astrocytic component of OAC may represent a focal area of Id4 expression in tumor subpopulations occurring at later stages after tumor initiation, leading to the co-expression of Id4 with OLIG1 and OLIG2 in neoplastic astrocytes and lack of Id4 expression in neoplastic oligodendrocytes." (PMID 16018821, 2005).
cancer (63 papers, 2005 to 2025). A tumor composed of atypical neoplastic, often pleomorphic cells that invade other tissues. "ID4 is intricately associated with cancer, with processes such as proliferation, differentiation, migration, and invasion involving numerous cancer types." (PMID 38327905, 2023). "We show experimentally that ID4 deletions are increased in RNase-H2-deficient cell lines and cancers and delineate a human TOP1-mediated TAM signature (ID-TOP1) that is relevant to both somatic and germline mutagenesis." (PMID 35140396, 2022). "ID4 was amplified at twice the frequency in BRCA1-mutant BLBC (~ 22%, 21/97 cases) compared to sporadic BLBC (~ 10%, 4/42 cases), indicating a selection for ID4 amplification in cancers arising in patients carrying a mutant BRCA1 allele." (PMID 32527287, 2020). "VEGFA then acts as the mediator that confers to ID4 protein in cancer cells the ability to cause ID4 induction in macrophages." (PMID 32054109, 2020). "ID4 has been previously associated with other human cancers, as both an oncogene and tumor suppressor gene." (PMID 25642713, 2015). "Among four types of Id proteins (Id1, Id2, Id3, and Id4), Id1 has been extensively studied in various cancers and is linked to tumorigenesis, as aberrant elevation of Id1 has been found in over 20 types of human cancer." (PMID 24970809, 2014). "An increase of Id4 expression was associated with the ability of ovarian (PA-1) and breast (SKBr3) cancer cells to exhibit anchorage-independent growth, while its depletion determined morphological change to a large and flat epithelial phenotype." (PMID 21293053, 2010). "This incidence of ID4 expression loss is very similar to the 78% of ID4 mRNA downregulation measured previously by a cancer profiling array." (PMID 18513385, 2008). "Quantitative analysis of GFP-positive cancer cells in lung tissue frozen sections revealed that ID4-silenced ELK3KD cells reacquired the ability to extravasate." (PMID 38188675, 2023). "Nevertheless, the precise mechanism governing the regulation of ID4 expression in cancer remains elusive." (PMID 38188675, 2023). "Although only present in three cancer types and a small fraction of tumors (3.2% of the cohort, n = 25 tumors), a significant correlation between ID4 activity and age at diagnosis has been observed." (PMID 36702933, 2023). "The epigenetic silencing of ID4 can lead to uncontrolled growth of cancer cells via this pathway, suggesting a role of ID4 silencing in tumorigenesis." (PMID 34298617, 2021). "Although the Id4 protein is involved in the regulation of cell cycle and cell senescence, its expression and functions remain controversial in some cancers." (PMID 33936204, 2021). "Id4 is one of the inhibitors of DNA-binding proteins (Id) and involved in the pathogenesis of numerous cancers." (PMID 33936204, 2021). "In our study the target genes are PAPSS2, SCD, and ID4 which play significant roles in various cancers." (PMID 34721037, 2021). "Although Id4 plays different roles in pathogenesis of various cancers, little is known about the functions of Id4 and its regulatory effects on the progression of CRC." (PMID 33936204, 2021). "Within this study, we observed that TNBC tissues showing high macrophage infiltration, evaluated using CD68 as a macrophage marker, presented ID4 protein expression not only in cancer cells but also in cells of the leukocyte infiltrate." (PMID 32054109, 2020). "In HG-SOC, inhibition of ID4 in vivo suppresses the growth of established tumors and significantly improves survival, suggesting that targeting ID4 expression is a viable therapeutic strategy in cancers that over-express ID4." (PMID 32054109, 2020).
cancer (continued). "To further investigate the role of Id4 in cancer metastasis, we established Id4 silencing and overexpressing stable cells and examined their cell invasiveness by modified Boyden chamber invasion assays." (PMID 31847356, 2019). "Collectively, we concluded that the expression of Id4 is inversely related to the regulation of cancer metastasis in vitro and in vivo." (PMID 31847356, 2019). "The function of Id4 has been identified as a paradigm shift compared with Id1-3 in different tissues during development and in cancer." (PMID 28974640, 2017). "Based on the sequence and structural property analyses, Id4 is a remote homologue of other Ids despite sharing the conserved HLH domain, which suggests a potential novel role for Id4 in the development of cancer." (PMID 28143562, 2017). "Studies have previously shown that epigenetic silencing of ID4 due to promoter hypermethylation appears to be the key mechanism in many cancers including prostate." (PMID 28252832, 2017). "As a member of the inhibitor of differentiation (Id) family, Id4 has been reported to function in many cancer types, but relatively little is known about its role in HCC." (PMID 28143562, 2017). "Inhibitor of DNA binding/differentiation protein 4 (ID4) is dominant negative helix loop helix transcriptional regulator is epigenetically silenced due to promoter hyper-methylation in many cancers including prostate." (PMID 25115397, 2014). "ID4 is involved in mammalian embryogenesis, angiogenesis and in the maintenance of cancer stem cells." (PMID 24475217, 2014). "The silencing of Id4 in cancers raises an important question: what is the normal physiological function of Id4 in at least those tissues which upon transformation leads to its loss of expression such as the prostate?" (PMID 23342267, 2012). "ID4 is a putative tumour suppressor gene that is down-regulated by hypermethylation in numerous cancers including ALL and MDS." (PMID 22348345, 2012). "The development and use of a highly selective antibody will thus ensure the quality and consistency of the data that will significantly advance our understanding of Id4 protein expression in cancers." (PMID 19500415, 2009). "In contrast to the putative oncogenic properties of ID1 and ID2, ID4 expression was found to be decreased in a variety of human cancers." (PMID 18513385, 2008). "ID4, a signature enriched for deletions (>1 bp) at repeats and microhomology, recently associated experimentally with TOP1 mutational activity in cancer and healthy cells, on the other hand was significantly more prevalent in non-high-risk patients (p < 1.68 × 10−3)." (PMID 37868040, 2023). "The effects of Id4 on the cell cycle and proliferation have been reported in some cancer cells." (PMID 33936204, 2021). "To address this, we first over-expressed HA-tagged ID4 protein in cancer cells, collected the CM and evaluated whether the ID4-HA protein was transferred to macrophages cultured with this CM." (PMID 32054109, 2020). "We previously reported that VEGFA expression is modulated by ID4 in cancer cells." (PMID 32054109, 2020). "However, we observed that depletion of ID4 in cancer cells only partially impairs the induction of ID4 in macrophages." (PMID 32054109, 2020). "ID4 is a newly discovered member in the ID family involved in various cellular processes in cancer." (PMID 32328189, 2020). "A caveat of this finding is that other cancer-associated genes, such as E2F3, are located adjacent to ID4 at Chr6q22 and so may also be a target of the amplification event." (PMID 32527287, 2020). "Herein, we explore the functional role of Id4 in cancer metastasis." (PMID 31847356, 2019). "The morphological changes led us to hypothesize that the effect of Id4 on cancer metastasis is related to the event of epithelial-mesenchymal transition (EMT)." (PMID 31847356, 2019).